VIM (vimentin)
Diseases named in the same sentence as VIM in open-access papers (continued):
Sharing a sentence is not in itself a finding about the gene and the disease.
cancer (continued). "As expected, a significantly (p = 0.035) higher percentage of vimentin-positive cells was also observed in complex and mixed malignant tumours (37% ± 3.9%) with respect to other malignant histotypes (26.9 ± 2.7%)." (PMID 36136722, 2022). "Inhibition of vimentin expression by shRNA was also sufficient to convert the resistant cancer cell lines to a sensitive phenotype." (PMID 36032170, 2022). "To analyze this, we quantified Snail, Twist (two frequently reactivated transcription factors in various cancers) and E cadherin and Vimentin (markers of cellular properties) in these cells." (PMID 35813483, 2022). "During the EMT process, cancer cells withdraw the epithelial markers (such as occludin and E-cadherin) and express mesenchymal markers (fibronectin, vimentin, and N-cadherin), which make the cancer cells mobile and disease aggressive." (PMID 35883447, 2022). "The regulation of Twist is also associated with the expression of membrane proteins (N-cadherin, fibronectin, and vimentin) involved in cell adhesion in cancer cells." (PMID 36547923, 2022). "In the present study, we described how hypoxia selectively induced the pro-invasive arm of TGFβ signaling through activation of a HDAC6- SMAD3-SARA-ITGB2/VIM pathway that contributes to the ability of cancer cells to invade and form metastases." (PMID 35681731, 2022). "Taken together, the discovery of potent vimentin‐targeting drugs is imperative in order to increase the translational potential of vimentin targeting as a therapy for cancers." (PMID 35766227, 2022). "This was accompanied by reduced expression of vimentin and fibronectin, which are both known to affect cell motility and metastasis in many cancer models." (PMID 35692807, 2022). "circ-0039459 knockdown or miR-432 overexpression can inhibit cell proliferation, invasion, and migration and the expression of N-cadherin and vimentin proteins in carcinoma cells as well as promote apoptosis and increase the E-cadherin level." (PMID 35543347, 2022). "The addition of TGF-β1 induces EMT (increased vimentin staining) and invasion across the basement membrane as a typical feature of carcinomas." (PMID 35565305, 2022). "Treatment of lung ACE2/A549 carcinoma cells with purified vimentin or coculture of ACE2/A549 cells with HEK-293 cells expressing vimentin increased ACE2-dependent viral entry." (PMID 35078919, 2022). "Vimentin supports cancer cell survival at metastatic sites by supporting angiogenesis via NOTCH signalling and calpains (proteolytic enzymes) which cleave the amino-terminal of vimentin; leading to a pool of soluble vimentin." (PMID 34638469, 2021). "Fibronectin coding genes were found to be up-regulated in studies describing cancer cell migration and various EMT markers such as vimentin, E-cadherin, MMP2 and MMP9, which were all associated with and used to measure cellular invasion." (PMID 33809554, 2021). "Recently, vimentin has been proposed as a biomarker for the use of cancer treatment and a druggable protein." (PMID 34203746, 2021). "Vimentin is prominently expressed in cells that are (or become) motile, including fibroblasts, mesenchymal cells, leukocytes and invasive cancer cells." (PMID 36046434, 2021). "Further, naringenin is able to inhibit cancer cell migration through the up-regulation of E-cadherin expression, but down-regulation of the expression of VIM, SNAIL family zinc finger 1(SNAI1), SNAIL family zinc finger 2(SNAl2)." (PMID 33842467, 2021). "During initial stages of cancer development, vimentin concentration is very low, however, it increases when cancer starts to invade the surrounding areas." (PMID 34638469, 2021). "Vimentin also interacts and reorganizes the keratin filaments and supports the desmosomal internalization and integrin recycling in cancers." (PMID 34638469, 2021). "As the major cytoskeletal component of mesenchymal cells, Vimentin has been used as a marker to identify the mesenchymal characteristics in cancer cells." (PMID 34326690, 2021).
cancer (continued). "Once cancer cells stop expressing epithelial markers, including E-cadherin, they start expressing mesenchyme markers, including N-cadherin and vimentin." (PMID 33430854, 2021). "E-cadherin, N-cadherin, and Vimentin are key players in the epithelial-mesenchymal process that is involved in cancer metastasis." (PMID 34931134, 2021). "Vimentin has a critical role in metastasis by stabilizing mature invadopodia, which is a prerequisite for invasive spread of cancer cells." (PMID 33465556, 2021). "Vimentin can regulate lymphocyte inflammatory responses and apoptosis in a cancer microenvironment by interacting with other inflammatory proteins, including heat shock protein 90 (HSP90), transmembrane protein 4 (TMP4) and 14-3-3 protein epsilon (YWHAE)." (PMID 34638469, 2021). "Withaferin-A, a naturally derived anti-cancer drug, works by apoptosis induction in vimentin expressing cancer cells." (PMID 33919917, 2021). "Phosphorylation of vimentin has been studied in mitotic dynamics, smooth muscle contractions, and cancer metastasis, revealing that phosphorylation is a main regulatory mechanism of its function through disassembly of IFs." (PMID 33963314, 2021). "We propose that latest technologies should be employed to medicinally target vimentin to reduce the cancer growth and its spread thereby helping to increase treatment outcomes and patients’ survival." (PMID 34638469, 2021). "Ser56 phosphorylation promotes disassembly of perinuclear vimentin, controlling filament stability and promoting cancer cell invasiveness." (PMID 36046434, 2021). "The epithelial phenotype of cancer cells, including E-cadherin expression, is lost, and the cells acquire interstitial phenotypes, characterized by N-cadherin and vimentin expression." (PMID 33997050, 2021). "Since integrins and vimentin play an important role in cancer cell metastasis, the protein expression levels were detected by Western blotting." (PMID 33403025, 2021). "We have tried to explore the potential new areas of research related to the role of vimentin in cancer progression." (PMID 34638469, 2021). "The results revealed that the expression of E-cadherin was decreased, while that of vimentin was increased in LoVo and Hct116 cells after ATO treatment compared to that of E-cadherin and vimentin in control cancer cells." (PMID 34676163, 2021). "Previously, we demonstrated that RAB7A regulates phosphorylation and assembly of vimentin, a cytoskeletal intermediate filament protein, which is also an important mesenchymal marker of cancer cells." (PMID 34066419, 2021). "Another EMT marker is vimentin, known as an important part of the cytoskeleton and a player in wound healing or metastasizing of cancer cells." (PMID 33803107, 2021). "Vimentin, as a canonical marker of epithelial to mesenchymal transition (EMT), is strongly associated with cancer invasive phenotype." (PMID 34305581, 2021). "The invasive front cancer cells express the mesenchymal marker vimentin but lack the epithelial marker E-cadherin, and exhibit mesenchymal attributes." (PMID 34483138, 2021). "In cancer cells undergoing EMT, higher vimentin levels are also linked with a dedifferentiated phenotype, whereas keratins are known markers of epithelial differentiation." (PMID 34638469, 2021). "High expression of vimentin correlates with the aggressiveness and poor clinical outcome in many types of cancers." (PMID 33757532, 2021). "The fact that surface vimentin expression correlated with CPMV uptake in this study demonstrated the ability of CPMV to detect invasive cancer cells." (PMID 34578279, 2021).
cancer (continued). "Enhanced levels of many cancer-related proteins are found in the CM of ET-1-treated cells, including MMPs, Snail, Tenascin-C, Vimentin, and downregulated levels of E-cadherin." (PMID 34926453, 2021). "D-CAN treatment also reduced the abundance of cancer cells expressing fibronectin and vimentin, reinforcing the notion that stromal ablation results in EMT suppression." (PMID 33753872, 2021). "MYOF depletion reversed the invasive morphology of cancer cells, as evidenced by reduced mesenchymal representative proteins (Fibronectin and Vimentin) and increased principal epithelial cell adhesion proteins (E‐cadherin and ZO‐1)." (PMID 33634965, 2021). "A model emerges in which elevated vimentin phosphorylation promotes IF disassembly, favoring cancer cell division." (PMID 36046434, 2021). "We further examined the effect of vimentin on cancer cell detachment by generating small short hairpin RNAs (shRNAs) targeting vimentin in A549 and PANC-1 cells." (PMID 34830801, 2021). "Although previous studies have identified fibroblasts as a main source of inflammatory cytokines, including CSF1, CSF1 expression was observed both in cancer epithelial cells and in vimentin positive cells." (PMID 33643790, 2021). "We also showed that recombinant vimentin stimulated a greater increase in cell migration rate in the MCF-7 cancer cells than for the MCF-10a cells." (PMID 34299089, 2021). "Changes in EMT markers such as matrix metalloproteinases 2 and 9 (MMP-2 and MMP-9), Vimentin, Snail, and E-Cadherin lead to the displacement of the cancer cell to the systemic environment, which further localized at distant places to form metastatic nodules." (PMID 34535685, 2021). "To underline the advantage and full flexibility of our device to also isolate cells by using variable cancer markers, we here targeted cell-surface vimentin (CSV) as an additional proof-of-concept example." (PMID 34829387, 2021). "In parallel, a cancer-associated fibroblast (CAF) signature was anchored by FAP, CAV1, VIM, and additional genes." (PMID 34518533, 2021). "Vimentin is required for plasticity of mesenchymal cells under normal physiological conditions and migration of cancer cells that have undergone epithelial/mesenchymal transition." (PMID 34595102, 2021). "All these 4 clusters were characterized by cancer stem-like cell phenotypes; Cluster 10 and 18 exhibited high levels of vimentin, ER-β and ICAM-1, positive expression of PD-L1." (PMID 34771607, 2021). "Changes in the levels or spatial organization of vimentin, an intermediate filament involved in cell adhesion, in cancer cells can lead to the stiffening of tumor tissues and alter the biomechanical properties of the TME." (PMID 33921421, 2021). "Vimentin also supports tubulin-based membrane protrusion called “microtentacles” that facilitate cancer cell adhesion and arrest on the vasculature." (PMID 33691719, 2021). "Expression of E-cadherin and Vimentin were previously monitored as surrogate markers to determine the epithelial and mesenchymal status of cancer cells during EMT, respectively." (PMID 33874986, 2021). "Consistent with in vivo observations, VIM-AS1 and Vimentin expression levels were dramatically upregulated in carcinoma cells and were more upregulated in high-metastatic cancer cell lines." (PMID 33902589, 2021). "Some studies have reported the facilitating role of vimentin in viral infections (such as hepatitis C and poliovirus) and associated chronic immune-inflammatory response, EMT and cancer." (PMID 34638469, 2021). "Additional immunofluorescence analyses were performed on HT-29 and MCF-7 spheroids, combining staining for CD68, CD11b, vimentin, and epithelial cell adhesion molecule (EpCam) to discriminate macrophages, fibroblasts, and cancer cells." (PMID 34451433, 2021). "This review highlights the varied roles of vimentin in cancer growth and its spread to distant areas of the body." (PMID 34638469, 2021).
cancer (continued). "In the present study, in the cell permeability assays, vimentin decreased the barrier permeability in MCF-7 cancer cells and increased it in MCF-10a cells." (PMID 34299089, 2021). "Vimentin is consistently observed to be overexpressed during cancer metastasis and is therefore generally acknowledged as a canonical biomarker of type-3 EMT." (PMID 34638469, 2021). "Our results show that autocrine TGF-β1- and vimentin-mediated cytoskeleton remodeling affects the adhesion and detachment of human cancer cells." (PMID 34830801, 2021). "WB demonstrated that E-cadherin expression was decreased and vimentin expression was increased in CAF-stimulated cancer cells by direct contact." (PMID 33462372, 2021). "Vimentin is upregulated during tumor progression, making it an attractive target for cancer therapy." (PMID 34578279, 2021). "Reportedly, it inhibits cancer cell migration and invasion, impairs the expression of mesenchymal markers (Vimentin, N-cadherin and fibronectin) and promotes the expression of epithelial marker E-cadherin." (PMID 34517910, 2021). "TGFβ1-dependent ARP2/3 and vimentin expression in cancer cells were attenuated in the presence of RUNX1 inhibitor (Ro5-3335)." (PMID 34376784, 2021). "Cancer stroma also prompts an increase in the expression of fibroblast-specific markers such as vimentin, fibroblast specific protein (FSP), and alpha smooth muscle actin (α-SMA), and a decrease in the expression of desmin." (PMID 33841508, 2021). "Further, we measured the protein levels of cancer cell metastasis-related markers (E-cadherin and vimentin) and the genes of interest (MEF2A and LEF1) were measured." (PMID 34957213, 2021). "The expression of important EMT markers (E-cadherin and vimentin) known to increase the invasive behaviour of cancer cells facilitating metastasis, was altered between the intervention and control group." (PMID 34948228, 2021). "Liprin-α1 knockdown leads to increased expression of vimentin in HNSCC cells, a component of intermediate filaments, as well as disturbances in organization of vimentin filament network in motile or metastatic cancer cells." (PMID 34654889, 2021). "It has been found that vimentin is also abnormally expressed in a variety of epithelial tumors, which is closely related to the differentiation, invasion and metastasis of cancer cells." (PMID 34093819, 2021). "From this study, we concluded that cancer cells tend to be more sensitive to extracellular vimentin, and hence that extracellular vimentin has an effect on general cellular functions." (PMID 34299089, 2021). "Strikingly, the TGFβ-induced expression of mesenchymal marker N-cadherin, EMT marker vimentin, and cancer stem cell marker Bmi1 was rescued by transient expression of La wildtype (LaWT) but not by the RCD activity-defective La mutant (LaΔRCD)." (PMID 33477794, 2021). "Vimentin is an intermediate filament protein that is known to be citrullinated and overexpressed in a wide range of cancers, particularly during EMT." (PMID 33859638, 2021). "The upregulation of vimentin and downregulation of E-cadherin expression are indicators of cancer invasiveness and metastasis." (PMID 34439333, 2021). "Taken together, these data indicate that vimentin can functionally interact with Akt to regulate cancer cell growth, migration and invasion." (PMID 34203746, 2021). "Snail activates EMT by reducing E-cadherin and claudins, and increasing vimentin and fibronectin in cancer." (PMID 34174900, 2021). "Vimentin silencing leads to the suppression of ITGβ4 mRNA and its protein, which suppresses cell migration and the invasive potential of the cancer cells." (PMID 34638469, 2021). "Our study provides a potential therapeutic strategy for cancer by targeting vimentin to block cancer exosome release." (PMID 34305581, 2021).
cancer (continued). "Cancer cells acquire motile features during EMT when mesenchymal markers such as vimentin, fibronectin, and N-cadherin are upregulated and epithelial markers like E-cadherin are downregulated." (PMID 34956878, 2021). "In the MCF-7 cancer cells, the migration rate upon 100 ng/mL vimentin and 100 ng/mL IGF-1 treatments, these reached 2.5 and 3 times higher than control respectively." (PMID 34299089, 2021). "Under compression, both the depletion of vimentin in human mesenchymal stem cells and the overexpression of vimentin in amoeboid cancer cells reduce cell deformation." (PMID 34440673, 2021). "VIM is an important marker for EMT and high expression levels correlate with a motile, mesenchymal-like cancer cell state, thus making VIM an essential effector of metastasis." (PMID 33706810, 2021). "In the network of cancer progression stimuli, vimentin is one of the most important proteins; it allows cancer cells to acquire metastatic phenotypes to invade other tissues." (PMID 33670389, 2021). "Proteins known to be associated with cancer or CSCs such as HSP90AB1, ALDH, vimentin, and AKR were upregulated in spheres and their expression was confirmed by western blot." (PMID 34794402, 2021). "In the case of PC, TGF-β-regulated vimentin levels were significantly associated with patients' BCR, with TGF-β3 ligand being more able to control the metastatic behavior of cancer cells." (PMID 34804366, 2021). "EMT is a trans-differentiation characterized as a key step toward cancer metastasis with decreased epithelial markers, such as E-cadherin, and increased mesenchymal markers, such as vimentin." (PMID 34367939, 2021). "During the last decade, VIMENTIN has received considerable attention regarding its role in cancer cell migration and invasion, signal transduction, and apoptosis." (PMID 35178358, 2021). "To study the potential of PFD in reducing invasive properties of carcinoma cells, we first co-cultured MCF7 carcinoma cells known as low-vimentin expressers with CAF-CM for 48 h and then treated cells with a low concentration of PFD (40 μM) for 72 h." (PMID 34680267, 2021). "These TFs have highly specific expression profiles and are known to upregulate Vimentin expression during EMT in several carcinomas." (PMID 33525953, 2021). "In fact, N-cadherin and Vimentin were found to be overexpressed in grade III carcinomas (p = 0.033 and p < 0.0001, respectively) and the triple-negative subtype (p = 0.001 and p < 0.0001, respectively)." (PMID 34680248, 2021). "The potential for targeting vimentin in cancer treatment and the development of drugs targeting vimentin will be reviewed." (PMID 31940801, 2020). "To date, only one—FiVe1—shows the real potential of specific vimentin targeting suitable for future cancer therapy." (PMID 31940801, 2020). "In particular, the expression of vimentin and TGF-β has been linked to poor disease-survival for several cancer patients." (PMID 31952346, 2020). "In turn, an RNA aptamer, P15, has been found to selectively bind vimentin on the surface of cancer cells and reduce tumorigenic behavior of pancreatic cancer cells." (PMID 32630064, 2020). "Lastly, we discuss the current possibilities of using vimentin as a potential drug target for cancer treatment." (PMID 31940801, 2020). "Data analysis also showed that Vimentin has increased with the growth of regional lymph nodes (pN category) in cancer tissues but in primary tumor (pT category) vimentin rate was not significant." (PMID 32665775, 2020). "In this review we will describe the role of vimentin intermediate filaments in cancer cell migration, cell adhesion structures, and metastasis formation." (PMID 31940801, 2020).